AFG2B (AAA ATPase AFG2B)
Description:
ATP-dependent chaperone part of the 55LCC heterohexameric ATPase complex which is chromatin-associated and promotes replisome proteostasis to maintain replication fork progression and genome stability. Required for replication fork progression, sister chromatid cohesion, and chromosome stability. The ATPase activity is specifically enhanced by replication fork DNA and is coupled to cysteine protease-dependent cleavage of replisome substrates in response to replication fork damage. Uses ATPase activity to process replisome substrates in S-phase, facilitating their proteolytic turnover from chromatin to ensure DNA replication and mitotic fidelity. Plays an essential role in the cytoplasmic maturation steps of pre-60S ribosomal particles by promoting the release of shuttling protein RSL24D1/RLP24 from the pre-ribosomal particles.
Synonyms: SPATA5L1; MGC5347; FLJ12286; DFNB119; NEDHLS
Tractability: PROTAC: ubiquitination databases record sites on it.
Target class: Enzyme; Hydrolase
Gene: Protein-coding gene on chromosome 15 (45,402,336 to 45,421,415, forward strand). Ensembl gene ENSG00000171763.
Subcellular location: Cytoplasm; Cytoplasm, cytoskeleton, spindle; Nucleus
Subcellular location (Human Protein Atlas): Nucleoplasm; Nucleoli
Gene Ontology:
Molecular function: identical protein binding; preribosome binding; protein binding; ATP hydrolysis activity; polyubiquitin modification-dependent protein binding; ATP binding; protein-containing complex binding
Biological process: DNA replication; regulation of ribosome biogenesis; ribosomal large subunit biogenesis; autophagosome maturation; mitotic spindle disassembly; proteasome-mediated ubiquitin-dependent protein catabolic process; retrograde protein transport, ER to cytosol
Cellular component: ATPase complex; cytoplasm; nucleus; spindle; VCP-NPL4-UFD1 AAA ATPase complex
Genetic constraint (gnomAD): Loss-of-function variants: 54 observed, 57.43 expected, observed/expected ratio (o/e) 0.94, 90% interval 0.75 to 1.18. The upper end of that interval is the gene's LOEUF score, 1.18, which puts it in group 5 of 6, group 1 being the genes least tolerant of losing a copy. Missense variants: 967 observed, 916.2 expected, observed/expected ratio (o/e) 1.06, 90% interval 1 to 1.11. Synonymous variants: 445 observed, 379.17 expected, observed/expected ratio (o/e) 1.17, 90% interval 1.09 to 1.27.
Gene-disease validity (ClinGen):
ClinGen rates the evidence that AFG2B causes each of these diseases.
hearing loss, autosomal recessive 119 (autosomal recessive): Limited.
Homologues: Orthologues: chimpanzee AFG2B (99% identical), macaque AFG2B (95% identical), dog AFG2B (88% identical), rabbit AFG2B (87% identical), pig AFG2B (86% identical), mouse Afg2b (80% identical), rat Afg2b (75% identical), guinea pig AFG2B (62% identical), tropical clawed frog afg2b (56% identical), zebrafish afg2b (50% identical), Caenorhabditis elegans cdc-48.1 (31% identical), Caenorhabditis elegans cdc-48.2 (31% identical), and 1 more. Paralogues in human: AFG2A (36% identical), VCP (34% identical), NVL (32% identical), PEX1 (28% identical), PEX6 (27% identical).
Diseases named in the same sentence as AFG2B in open-access papers:
AFG2B is named in the same sentence as 17 diseases in open-access papers, as found by Europe PMC text mining. Sharing a sentence is not in itself a finding about the gene and the disease. The quoted sentences say what the papers report.
hearing loss (2 papers, 2024 to 2025). "In total, 28 bi‐allelic variants in AFG2B in 47 individuals with hearing loss have been reported so far." (PMID 37902276, 2024). "Neurogenetic disorders with combined developmental and auditory phenotypes, including AFG2A (SPATA5) and AFG2B (SPATA5L1)–related syndromes, are increasingly recognized within a broader spectrum of neurogenetic hearing loss." (PMID 41375745, 2025). "Recently, bi‐allelic variants in AFG2B have been associated with neurodevelopmental disorder with hearing loss and spasticity (OMIM #619616), as well as with isolated hearing loss (OMIM #619615)." (PMID 37902276, 2024).
Intellectual disability (2 papers, 2024 to 2025). "Of note, human genetic studies have identified a growing number of allelic variants in AFG2A, AFG2B and CINP that are specifically associated with a range of NDDs, including intellectual disabilities, seizures, hearing loss and microcephaly." (PMID 40760247, 2025).
neurodevelopmental disorder (4 papers, 2024 to 2025). A behavioral and cognitive disorder with onset during the developmental period that involves impaired or aberrant development of intellectual, motor, or social functions. "Bi‐allelic variants in AFG2B (previously known as SPATA5L1) have recently been associated with a neurodevelopmental disorder with hearing loss and spasticity, as well as isolated hearing loss." (PMID 37902276, 2024). "We report on a 6 1/2‐year‐old girl with a neurodevelopmental disorder carrying compound heterozygous missense variants in AFG2B [c.527G>T, p.(Gly176Val) and c.1313T>C, p.(Leu438Pro)]." (PMID 37902276, 2024). "In a 6 1/2‐year‐old girl with a neurodevelopmental disorder, we identified compound heterozygous variants in AFG2B [c.527G>T, p.(Gly176Val) and c.1313T>C, p.(Leu438Pro)] by using trio exome sequencing." (PMID 37902276, 2024).
AFG2B also shares sentences with these, for which no sentence is quoted: microcephaly (4 papers); developmental delay (2); Dystonia (2); cancer (1); cervical cancer (1); chronic kidney disease (1); epilepsy (1); Hearing impairment (1); lupus (1); lupus nephritis (1); melanoma (1); movement disorder (1); nephritis (1); Nephropathy (1).